RELB (RELB proto-oncogene, NF-kB subunit)
Diseases named in the same sentence as RELB in open-access papers (continued):
Sharing a sentence is not in itself a finding about the gene and the disease.
tumor (continued). "RM-1, RM-1:RelB-KO and RM-1:RelB-KO/PD-L1 cell lines were used for tumour formation by subcutaneous injection into mice." (PMID 35177112, 2022). "Although CD4+ and CD8+ T cells were high in the RelB-KO group, the cell numbers declined as PD-L1 expression increased in tumour cells." (PMID 35177112, 2022). "Intriguingly, the results from this study elucidated, for the first time, that tumour-derived RelB hampers T cell function by upregulating PD-L1." (PMID 35177112, 2022). "Accordingly, the repression of tumour-derived RelB can promote the T cell immune response by downregulating PD-L1." (PMID 35177112, 2022). "Male mice were injected with murine PCa cells to validate the effect of RelB on the PD-1/PD-L1-mediated immune checkpoint using both tumour growth and metastatic experimental models." (PMID 35177112, 2022). "We also have shown that RelB expression increases tumorigenicity in a mouse PCa xenograft tumor model." (PMID 35742868, 2022). "For example, RelA promotes cell proliferation while RelB supports viability of tumour-initiating cells, and both act to promote spheroid formation." (PMID 35194062, 2022). "A mouse tumour xenograft model was applied to define the role of RelB in the immune checkpoint of PD-1/PD-L1." (PMID 35177112, 2022). "Our current study does demonstrate a differential expression of RelB in tumor vs. normal cells after exposure to P-AscH−, both with and without radiation." (PMID 33923601, 2021). "Altogether, RelB plays a critical role in tumor progression through the induction of the proneural to mesenchymal transition." (PMID 34198987, 2021). "The NF-κB signaling pathway comprises a family of five transcription factor subunits (p65/RelA, c-Rel, RelB, p50/NF-κB1, and p52/NF-κB2), which are key regulators of tumor cell growth, proliferation, metastasis, and chemotherapy resistance." (PMID 34976812, 2021). "The statistical analytic data indicated that the mRNA levels of RelA and RelB in tumor tissues were higher than their levels in normal breast tissues, particularly the difference in RelB levels appeared to be highly associated with BCa progression." (PMID 32807176, 2020). "We next checked the expression level of RelB in tumor samples of previous xenografts finding that the RelB seemed to positively correlate with the G9a levels and tumor volume." (PMID 32477831, 2020). "Compared to the control group, tumor aggressiveness stain Ki67 was significantly reduced in the RelB-knocked out group." (PMID 32807176, 2020). "Two mouse xenograft tumor experimental models were used to validate the effects of RelB on tumor growth and metastasis in vivo." (PMID 32807176, 2020). "Compared to injection of the control cells, tumor formation by the RelB-knocked out cells was approximately 1 week late." (PMID 32807176, 2020). "The present study demonstrates that the high level of constitutive RelB is necessary for BCa progression by enhancing both tumor growth and metastases." (PMID 32807176, 2020). "BCa tumor tissues and the corresponding cell lines were examined to determine the correlation between RelB and the aggressiveness of BCa." (PMID 32807176, 2020). "While RELA overexpression promoted tumor growth and vice-versa, RELB overexpression decreased tumor growth." (PMID 31602271, 2019). "The expression of both RelA/p65 and RelB were increased in cells grown under a tumor-initiating cell (TIC) culture and both were required for sphere formation in vitro." (PMID 31443240, 2019). "Although phosphorylated Akt was only seen in small fraction (3.5%) of tumor cells, nuclear translocation of NF-κB such as p105/50, p100/52, p65 and RelB was observed, and the nuclear positive percentages were 70.6%, 82.2%, 84.4% and 82.5%, respectively." (PMID 31015491, 2019).
tumor (continued). "The oncogenic or tumor suppressor functions of RelA, c-Rel, and RelB can be highly context-specific, showing variation not only in different cell types but also depending on the stage of malignant transformation." (PMID 31277415, 2019). "RelB has been reported to function in the spontaneous or radiotherapy-induced apoptosis in tumor cells.." (PMID 30473630, 2018). "High RelB expression strongly correlates with rapid tumour progression and poor patient survival rates." (PMID 29983639, 2018). "These analyses indicated that poor tumor differentiation and high RelB expression were independent factor for shorter OS in CRC patients." (PMID 30473630, 2018). "Univariate survival analyses indicated that tumor differentiation (p < 0.001), N stage (p = 0.001), M stage (p = 0.001), pTNM stage (p < 0.001), and RelB expression (p = 0.002) had statistical significances." (PMID 30473630, 2018). "In vivo, RelB silencing inhibited the volume and weight of subcutaneous tumours established by the subcutaneous xenograft model." (PMID 29983639, 2018). "Our previous studies reported that the high levels of nuclear RelB in PCa contribute to tumor metastatic progression and resistance to radiation." (PMID 30053873, 2018). "In adenocarcinoma tissues, the expression of RelB was detected in both the nucleus and the cytoplasmic portions of the tumour cells, while the expression of RelB was nearly undetectable in the adjacent non-neoplastic tissues." (PMID 29983639, 2018). "Histological analyses of tumours formed were carried out to confirm the expression of RelB in the xenografts." (PMID 29983639, 2018). "In present study, we found that RelB expression was positively related to depth of tumor invasion, lymph node metastasis, metastasis stage, and pTNM stage." (PMID 30473630, 2018). "High RelB expression was significantly correlated with depth of tumour invasion (p = 0.010), lymph node metastasis (p = 0.048), distant metastases (p = 0.006), and TNM stage (p < 0.001) in patients with NSCLC." (PMID 29983639, 2018). "Enhancer of zeste homology 2 (EZH2) can promote the transcriptional activation of RelB, driving self-renewal and tumor-initiating cell phenotype of triple-negative breast cancer cells." (PMID 30473630, 2018). "In primary NSCLC samples, RelB expression was increased in tumour tissue both at the mRNA and protein levels." (PMID 29983639, 2018). "NF-κB subunit expression was also examined in respect to tumor grade, revealing no changes in RelA and P100/P52 expression, but enhanced P50 and RelB expression with increasing tumor grade." (PMID 29371965, 2017). "In line with our findings in tumor cells, we detected an increase in RelB and IκBα mRNA levels, also indicating an activation of NF-κB signaling in SM-treated NK cells." (PMID 28326081, 2017). "NFκB transcription factors are homodimers or heterodimers of NFκB1 (p50), NFκB2 (p52), RelA (p65), RelB, or cREL, and have been widely reported to participate in tumor initiation, cell proliferation, apoptosis, chemoresistance, and the EMT." (PMID 26942699, 2016). "It has also been reported that RelB overexpression in the LnCaP prostatic cell line, whose the basal classical NF-κB activity is moderate, promotes the in vivo tumor growth into murine model and increases the ability to form colonies in soft agar." (PMID 26186215, 2015). "The nuclear frequency of p65 was found to be significantly increased in tumor tissues as compared with normal adjacent tissue, whereas the frequency for RelB was decreased (p < 0.001, Wilcoxon test)." (PMID 26186215, 2015). "These analyses revealed that RelB was the subunit expressed the strongest in areas of tumor cells displaying a both nuclear and cytoplasmic expression pattern." (PMID 26147201, 2015). "The lag in the tumor initiation observed with RelB-22Rv1 cells is in contrast with previous studies reporting that LNCaP xenografts expressing RelB grow faster than the parental LNCaP cells." (PMID 25788857, 2014).
tumor (continued). "Our data showed that RelB expression in C2-RelB and C3-RelB cells increased significantly the time of tumor initiation compared to GFP-control cells." (PMID 25788857, 2014). "The statistically significant variation in 22Rv1-RelB tumors between C2 or C3 and C1 that weakly expressed RelB supported the role of RelB in the tumor growth rates (respective comparison C1/C2 and C1/C3; P = 0.019 and P = 0.021, Tukey’s test)." (PMID 25788857, 2014). "The integration of our in vitro and in vivo results lead us to propose a model of RelB function during tumor initiation and progression in the xenograft mouse model." (PMID 25788857, 2014). "In vitro results showed that RelB expression decreased the anchorage-independent growth of 22Rv1 cells, which correlated with the lag of tumor initiation of RelB-expressing xenografts." (PMID 25788857, 2014). "The in vivo observations on tumor initiation and progression led us to explore different in vitro cell processes to better understand the impact of RelB in PCa cells." (PMID 25788857, 2014). "The relevance of our studies for human disease was confirmed by analysis of a human GBM genome database, which revealed that high RelB expression strongly correlates with rapid tumor progression and poor patient survival rates." (PMID 23451236, 2013). "Although both classical and alternative pathways are activated by coculture of MM cells with BMSCs, the relative contribution of the microenvironment in mediating RelB activation in MM tumor cells is poorly understood and worth further investigation." (PMID 23555623, 2013). "Compared to the control siRNA group, tumor growth in the RelB knock-down group was significantly slower than in the control siRNA group." (PMID 22403723, 2012). "In the control siRNA group, the average time for a tumor to reach 500 mm3 was 11±2.1 days, whereas the average time in the RelB knock-down group extended to 26±5.1 days." (PMID 22403723, 2012). "The effects of siRNA-mediated knock-down of RelB were confirmed by Western blot analyses of RelB and IL-8 in the tumor tissues." (PMID 22403723, 2012). "Furthermore, inhibition of IGF2BP2 and RELB suppressed HCC tumor progression both in vitro and in vivo." (PMID 42096134, 2026). "Based on the available data, combining agents that inhibit PD-L1 expression and enhance anti-tumor immune responses—such as NRP2 or RelB inhibitors—with existing regimens may further improve therapeutic efficacy in prostate cancer." (PMID 41488631, 2025). "However, STING-dependent activation of NF-κB RelB-IL-6-STAT3 was shown to promote tumor cell proliferation by blocking STAT1-induced apoptosis." (PMID 40691137, 2025). "Target genes of non-canonical NF-κB pathway have been shown to include BLIMP-1 (via RelB, albeit in tumor cells), suggesting this gene may be an early regulator of the exhaustion transcriptional network." (PMID 39689157, 2024). "Cells with high levels of RelB or IL‐8 fostered tumour growth and dissemination in the mice." (PMID 39415352, 2024). "In summary, RelB served as an oncogene in the process of tumor genesis in different cancers." (PMID 37388242, 2023). "Taken together, RelB was of great value in predicting tumor prognosis." (PMID 37388242, 2023). "We next checked whether genes of the tumor progression-related NF-κB signature evidenced in BRAF-PTCs were actually regulated by RelA or RelB in BRAFV600E cell line models." (PMID 37973791, 2023). "In addition, the alteration of PD‐L1 in tumor tissues was concomitant with elevated RelB, which contributed to the regulation of PD‐L1 expression." (PMID 37501397, 2023). "In contrast, tumour formation in the RelB-KO group was delayed and tumour growth was also slow." (PMID 35177112, 2022).
tumor (continued). "Transcription factor (TF) activity prediction, using the DoRothEA resource, to identify potential regulons responsible for the signalling and phenotypes associated with HPS in HiFi tumours revealed a strong association with STAT1, STAT2, IFN (IRF1, IRF9) and NFκB (NFKB1, REL, RELA, RELB) TFs." (PMID 35477539, 2022). "The results indicated that PD-L1 is more highly associated with RelB than RelA in PCa tumour tissues, but no clear correlation was found in peritumoral tissues." (PMID 35177112, 2022). "In GC, NFKB1, NFKB2, REL, RELA, and RELB were significantly upregulated in tumor tissues." (PMID 35036435, 2022). "Thus, the implication of RelB in both immune cells and tumour cells has emerged as a major concern for tumour immunotherapy." (PMID 35177112, 2022). "Nevertheless, the tumour growth in the RelB-KO/PD-L1 group was restored due to increased PD-L1." (PMID 35177112, 2022). "Furthermore, in metastatic cases with LBD above 15 mm, tumour thickness exceeding 8 mm and higher tumour staging, the expression of p52 and RelB was significantly increased." (PMID 35008260, 2021). "Interestingly, expression of colony stimulating factor 1 (CSF1), CSF2, CSF3, C-C motif ligand 2 (CCL2), CCL7, and C-X-C motif ligand 2 (CXCL2), which promote myeloid cell recruitment and drive tumor progression, was dependent on RelB." (PMID 34198987, 2021). "Furthermore, there is a clear distinction between the uniformly RelB-positive tumor cells versus RelB-negative stromal cells." (PMID 34292968, 2021). "Furthermore, overexpression of RelB in G9a-depleted MM cells rescued tumor growth rate in vivo in MM xenograft mouse models." (PMID 32477831, 2020). "A correlation between RelB and NF-κB2 expression with clinicopathological parameters, including a patient's race, gender, age, weight, tumor grade, cancer stage, and nodal metastasis status, revealed significant upregulation of RelB and NF-κB2 in HCC, relative to normal liver tissues." (PMID 32879628, 2020). "Additionally, tumor images by hematoxylin and eosin (H&E) staining confirmed that the metastasized tumors were obviously reduced in the RelB-knocked out group compared to the control group." (PMID 32807176, 2020). "Additionally, the enforced expression RelB in MCF-7 cells was still insufficient to tumor metastasize to the lung." (PMID 32807176, 2020). "However, the tumor growing speed and tumor weight were remarkably reduced in the group injected with the RelB-knocked out cells." (PMID 32807176, 2020). "Apart from that, MCPIP1 is recognized as a tumor suppressor due to its induction of apoptosis of tumor cells, for instance by selectively enhancing mRNA decay of antiapoptotic gene transcripts, including Bcl2L1, Bcl2A1, RelB, Birc3, and Bcl3." (PMID 31651935, 2019). "In SCID mice, RelB overexpression leads to a lag in the initiation of 22Rv1-induced tumours." (PMID 29983639, 2018). "Multivariate Cox regression analyses indicated that tumor differentiation and RelB expression had statistical significances, with hazard ratio (HR) of 2.115 for tumor differentiation (95% CI 1.044–4.286, p = 0.038) and 2.996 for RelB (95% CI 1.848–6.047, p = 0.002)." (PMID 30473630, 2018). "Taken together, these results reveal a tumour-supportive role of RelB in NSCLC." (PMID 29983639, 2018). "Usually, RelB functions as an oncogenic driver of tumour cell survival." (PMID 29983639, 2018). "Interestingly, RelA overexpression promoted tumor growth, whereas RelB overexpression decreased tumor growth." (PMID 29874793, 2018). "Thus, advanced G1-to-S progression and the prevention of apoptosis act in concert to fuel accelerated tumor growth in the presence of tumor cell-intrinsic RelB." (PMID 27711077, 2016). "NF-κB is member of a family of proteins including RelA (p65), RelB and c-Rel that form homo- or heterodimers and bind to specific sequences in promoter regions in response to extracellular stimuli, such as inflammation, cytokines, and tumor promoters." (PMID 27791197, 2016).
tumor (continued). "Moreover, tumor cell-intrinsic RelB was responsible for the abundant levels of c-Myc, cyclin D1, Bcl-2 and Bcl-xL, which are key regulators of cell cycle transition, apoptosis and proliferation in EEC." (PMID 27711077, 2016). "Since RelB expression has been found to be regulated by both the canonical as well as the alternative NF-κB pathways, we next sought to examine a possible correlation between RelA expression in tumor or stroma compartments, and RelB expression in tumor cells." (PMID 26147201, 2015). "Interestingly, tumor RelA expression was correlated with inflammatory infiltration and tumor RelB expression was collocalized with proliferating tumor cell nuclei." (PMID 26147201, 2015). "Importantly, tumor area RelA expression was correlated with the intensity of inflammatory infiltration, whereas RelB expression was identified in proliferating tumor cells." (PMID 26147201, 2015). "In specific, RelB was highly expressed in tumor cells, while RelA and P50 in stromal cells." (PMID 26147201, 2015). "For instance, data from our group suggest that the nuclear distribution of the alternative NF-κB subunits RelB and p100/p52 in tumor tissues of PCa patients correlates with an activation of the alternative NF-κB pathway and potentially involved in PCa progression." (PMID 25788857, 2014). "Together, these results suggest that the overexpression of RelB caused a lag in tumor initiation without affecting the overall tumor growth." (PMID 25788857, 2014). "Thus, our results strongly suggest that increased cIAP2 expression is directly controlled by RelB heterodimers in MM tumor cells." (PMID 23555623, 2013). "Our study has revealed that RelB promotes tumor cell survival in MM." (PMID 23555623, 2013). "Interestingly, IR not only controlled tumor regrowth, but it also reduced tumor size in the RelB siRNA group." (PMID 22403723, 2012). "Moreover, since RELB is directly involved in the NK-κB pathway, it is tempting to postulate a role for RNASET2 in RELB-mediated control of tumor-associated macrophages (TAM) polarization." (PMID 21646684, 2011). "NF-κB transcription factor family is involved in diverse biological processes enabling tumor development and resistance to anticancer-therapy through activation of its two main pathways, the canonical and the alternative NF-κB pathways, the main actor of the latter being the RelB NF-kB subunit." (PMID 35203557, 2022). "Thus, it is likely that the pro-survival effects of RelB upon metabolic stress may be generalized to other neoplasms, especially those addicted to alternative NF-κB." (PMID 35203557, 2022). "Moreover, to examine whether RelB deprivation also inhibits PCa metastasis by downregulating PD-L1, the three tumour cell lines were further injected into mice through the tail vein." (PMID 35177112, 2022). "Notably, RelB is overexpressed in the mesenchymal fraction of some tumor types, so we assessed whether ADSCs could increase stemness in HeLa cells." (PMID 32848147, 2020). "In a comparative study of shRNAs targeting RelA or RelB, OC cells grown in tumor-initiating cell (TIC) culture conditions had significantly fewer Ki67 positive, proliferative cell populations and reduced viability with loss of RelA, compared with the loss of RelB." (PMID 31443240, 2019). "Interestingly, RelB expression increased with tumor stage, grade, and local extent." (PMID 29371965, 2017). "Thus, regulation of the cell cycle and apoptosis by RelB in EEC contributes to our knowledge of early tumor development, and drugs specifically targeting RelB may represent a new strategy to combat EC." (PMID 27711077, 2016). "However, RelA and P50 were predominantly expressed in intratumoral stroma, but RelB in tumor cells." (PMID 26147201, 2015).